LINC01094 (long independently transcribed non-coding RNA 1094)
Synonyms: CTEPHA1; lincRNA-ANXA3; LOC101928893
Gene: Long non-coding RNA gene on chromosome 4 (78,623,173 to 78,769,640, forward strand). Ensembl gene ENSG00000251442.
Diseases named in the same sentence as LINC01094 in open-access papers:
LINC01094 is named in the same sentence as 27 diseases in open-access papers, as found by Europe PMC text mining. Sharing a sentence is not in itself a finding about the gene and the disease. The quoted sentences say what the papers report.
ovarian carcinoma (14 papers, 2020 to 2025). A malignant neoplasm originating from the surface ovarian epithelium. "In ovarian cancer, the LINC01094/miR-577 axis regulates the expression of a β-linked protein, c-Myc, and cell cycle protein D1, promoting cancer cell proliferation, invasion, and migration." (PMID 36935487, 2023). "LINC01094 is associated with the prognosis of ovarian cancer, pancreatic cancer, glioma, and renal clear cell carcinoma." (PMID 36186426, 2022). "The results indicated that compared with the normal ovarian cell line HOSEPIC, the expression of LINC01094 in the three ovarian cancer cell lines was significantly upregulated (P<0.05)." (PMID 37859811, 2023). "LINC01094 facilitated cell invasion via targeting miR-532-3p and Wnt/b-catenin pathway in ovarian cancer." (PMID 37597098, 2023). "Recent studies have also pointed that LINC01094 promotes the malignant phenotype of kidney cancer, glioma, and ovarian cancer." (PMID 36831602, 2023). "Other studies have found that LINC01094 is significantly upregulated in ovarian cancer (OC) tissues and cells." (PMID 36824662, 2023). "Previous studies report that LINC01094 is abnormally expressed and acts as a tumor promoter in several cancers, including ovarian cancer and clear cell renal cell cancer; overexpression of LINC01094 promotes cell proliferation, migration, and invasion." (PMID 34657558, 2021). "LINC01094, also called CTEPHA1, was previously linked to chronic thromboembolic pulmonary hypertension and has since been implicated in the malignant phenotypes of kidney cancer, glioma, and ovarian cancer." (PMID 40438104, 2025). "Previous research has indicated that LINC01094 can facilitate the progression of numerous cancers, including ovarian cancer, clear cell renal cell carcinoma, and glioma through various mechanisms; however, its role in HCC remains unclear." (PMID 36873490, 2023). "LINC01094 was reported to regulate the ovarian cancer progression via modulation of miR-577." (PMID 37597098, 2023). "LINC01094 was known for their regulatory function in glioblastoma and ovarian cancer." (PMID 37597098, 2023). "LINC01094 could promote the progression of ovarian cancer, breast cancer, pancreatic cancer, and other cancers." (PMID 36467998, 2022). "LINC01094 has been demonstrated to enhance the invasion, migration, and EMT capabilities of ovarian cancer cells by adsorbing miR-577." (PMID 35330731, 2022). "qRT-PCR analysis revealed significantly higher expression levels of PRR34_AS1, LINC01094, SPAG5_AS1, AC106801.1, and CACNA1G_AS1 in ovarian cancer cell lines (Caov-3, HO-8910PM, OVCAR3, and SKOV3) compared to HOSEpiC, a cell line of normal ovarian cells (p < 0.05)." (PMID 38226979, 2024). "Thus, we discovered many unproven pyroptosis related regulatory axes in ovarian cancer, such as KRT7-AS—has-miR-205—GSDMC, LINC01094—has-miR-330-3p—IRF1, ZNF32-AS2—has-miR-214—GSDME, and MYCNOS—has-miR-150—NLRP1." (PMID 37859811, 2023).
clear cell renal cell carcinoma (11 papers, 2020 to 2023). "Targeting the miR-577/CHEK2/FOXM1 axis, LINC01094 promotes radioresistance in clear cell renal cell carcinoma (ccRCC)." (PMID 36568382, 2022). "LINC01094 facilitates clear cell renal cell carcinoma radioresistance by targeting the miR-577/CHEK2/FOXM1 axis." (PMID 35047414, 2021). "LINC01094 is proved to be a ceRNA for miR-224-5p in clear cell renal cell carcinoma, and it increases the translation of oncogene CHSY1 via competitively binding to miR-224-5p." (PMID 33069244, 2020). "There is a high expression of LINC01094 in clear cell renal cell carcinoma (ccRCC)." (PMID 36824662, 2023). "Besides, LINC01094 could promote clear cell renal cell carcinoma development through the miR-224-5p/CHSY1 regulatory axis." (PMID 34819945, 2021). "For example, LINC01094 was found to upregulate SLC2A3 by targeting microRNA-184, subsequently promoting the development of clear cell renal cell carcinoma." (PMID 35568824, 2022).
breast carcinoma (8 papers, 2021 to 2025). "There is a correlation between high LINC01094 expression and shorter overall survival for breast cancer patients." (PMID 36824662, 2023). "Other studies have found that LINC01094 is more abundant in breast cancer tissues than in normal tissues." (PMID 36824662, 2023). "LINC01094 induces cell cycle progression by regulating the microRNA-340-5p (miR-340-5p)/E2F transcription factor 3 (E2F3) molecular axis, as a result, facilitating the spread and progression of breast cancer cells." (PMID 36824662, 2023).
glioma (8 papers, 2021 to 2025). A benign or malignant brain and spinal cord tumor that arises from glial cells (astrocytes, oligodendrocytes, ependymal cells). "The expression of LINC01094 in glioma tissues and cell lines is highly correlated with high-grade gliomas, according to some studies." (PMID 36824662, 2023). "A miR-330-3p/MSI1 axis is regulated by LINC01094 to promote glioma cell proliferation, migration, and invasion." (PMID 36824662, 2023). "Linc01094 promotes proliferation, migration and invasion of glioma cells by adsorbing miR-330-3p and upregulating MSI1 expression." (PMID 34819945, 2021). "In agreement with our findings, glioma and schizophrenia, two additional nervous system diseases, exhibit significantly higher expression levels of ASB16-AS1 and LINC01094, respectively." (PMID 36324503, 2022).
pancreatic cancer (6 papers, 2022 to 2024). "In addition, further studies have found that LINC01094 is overexpressed in pancreatic cancer." (PMID 36824662, 2023). "LINC01094 regulates lin-28 homolog B (LIN28B) expression and PI3K/AKT pathway serving as a ceRNA of miR-577, which promotes the proliferation and metastasis of pancreatic cancer." (PMID 36824662, 2023).
gastric cancer (4 papers, 2022 to 2025). A primary or metastatic malignant neoplasm involving the stomach. "Some studies have found that LINC01094 is highly expressed in gastric cancer tissues and is an independent index to estimate adverse survival rate." (PMID 36824662, 2023). "LINC01094 expression predicted poor prognosis in patients with gastric cancer and was correlated with the macrophage infiltration." (PMID 36338651, 2022). "LINC01094 could participate in epithelial-mesenchymal transition (EMT) and tumor-associated macrophages (TAMs) infiltration of gastric cancer to promote the progression and metastasis of gastric cancer." (PMID 36824662, 2023).
chronic thromboembolic pulmonary hypertension (2 papers, 2023 to 2025). Chronic thromboembolic pulmonary hypertension (CTEPH) is characterized by the persistence of thromboemboli in the form of organized tissue obstructing the pulmonary arteries. "LINC01094, also known as CTEPHA1, has been associated with chronic thromboembolic pulmonary hypertension in a previous study." (PMID 36831602, 2023).
glioblastoma (2 papers, 2022 to 2023). The most malignant astrocytic tumor (WHO grade IV). "Likewise, LINC01094 was reported to promote the tumorigenesis and metastatic phenotypes of glioblastoma cells as a ‘sponge’ for miR-126-5p." (PMID 35287563, 2022).
lung adenocarcinoma (2 papers, 2022 to 2023). A carcinoma that arises from the lung and is characterized by the presence of malignant glandular epithelial cells. "LINC01094 increased the expression of CCL7 in lung adenocarcinoma by binding to the transcription factor SPI1 of CCL7 and promoting its translocation into the nucleus, thus increasing the degree of infiltration of macrophages in lung adenocarcinoma." (PMID 37637063, 2023).
colorectal cancer (1 paper, 2023). A primary or metastatic malignant neoplasm that affects the colon or rectum. "LINC01094 can promote the progression of colorectal cancer by regulating the miR-1266-5p/secretory leukocyte protease inhibitor (SLPI) axis." (PMID 36824662, 2023). "In addition, studies have found that LINC01094 is highly expressed in colorectal cancer cells." (PMID 36824662, 2023).
lung carcinoma (1 paper, 2022). "The LINC01094 has been linked to development and progression of several cancer types, though its specific role in lung cancer remains undefined yet." (PMID 36118415, 2022).
lymph node metastasis (1 paper, 2020). "High LINC01094 expression was associated with higher FIGO stage, lymph node metastasis and the shorter overall survival rate in patients with OC." (PMID 33069244, 2020). "Additionally, high LINC01094 expression was associated with advanced FIGO stage, lymph node metastasis and poor overall survival rate." (PMID 33069244, 2020).
Lymphatic Metastasis (1 paper, 2020). Transfer of a neoplasm from its primary site to lymph nodes or to distant parts of the body by way of the lymphatic system. "As shown, the expression of LINC01094 in patients with higher FIGO stage and lymphatic metastasis was markedly higher than that in patients with lower stage and no lymphatic metastasis." (PMID 33069244, 2020).
metastasis (1 paper, 2020). The spread or migration of cancer cells from one part of the body (where they first appeared) to another. "Additionally, the expression of LINC01094 was not related with the patient’s gender, age, and tumor size (all p > 0.05); however, it was related to the TNM stage, Fuhrman grade, vascular invasion, and lymph node metastasis (all p < 0.05)." (PMID 33173535, 2020).
prostate carcinoma (1 paper, 2023). A carcinoma that arises from epithelial cells of the prostate gland. "LINC01094 is in conjunction with a poor prognosis, in various cancer types, but its effect on the prostate cancer microenvironment is still unclear." (PMID 36824662, 2023).
renal carcinoma (1 paper, 2022). A carcinoma arising from the epithelium of the renal parenchyma or the renal pelvis. "The results showed that the expressions of RNF139-AS1, SRD5A3-AS1, LINC01094, USP30-AS1, LACTB2-AS1, and LINC01355 were elevated in renal carcinoma cells, and the expressions of RAP2C-AS1 and LINC00551 were reduced in renal carcinoma cells compared with normal renal proximal convoluted tubule cells." (PMID 35664432, 2022).
renal cell carcinoma (1 paper, 2021). "LINC01094 expression is elevated in renal cell cancer tissues and cells, and LINC01094 overexpression down-regulates miR-577 expression and promotes the translation of FOXM1 mRNA, by which it increases the radioresistance of renal cell carcinoma cells." (PMID 34657558, 2021).
tumor (24 papers, 2020 to 2026). "For the stage III–IV subgroup, using 2.5 as the cutoff tumor/normal tissue expression fold, high LINC01094 expression was still associated with an unfavorable prognosis." (PMID 36831602, 2023). "Although only 9 GC samples were included in the database, the data showed that LINC01094 was highly expressed in plasma exosomes of at least some GC patients, suggesting that GC exosomal LINC01094 may be a potential mechanism underlying M2 macrophage polarization during tumor progression." (PMID 39525623, 2024). "LINC01094 was predominantly localized in the cytoplasm and was upregulated in tumor tissues compared with adjacent normal tissues, acting as an unfavorable prognostic factor." (PMID 40438104, 2025). "LINC01094 expression was significantly higher in tumor samples than in adjacent normal tissues in our cohort of ten matched pairs, and it was also elevated in BLCA cell lines compared with normal uroepithelial cells." (PMID 40438104, 2025). "Taken together, these data suggest that LINC01094 promotes glycolytic metabolic reprogramming and tumor progression in BC both in vitro and in vivo." (PMID 40470773, 2025). "Silencing of LINC01094 expression significantly curtailed the local infiltration capability of xenografts, with tumor nodules in the LV‐sh LINC01094 group exhibiting improved encapsulation." (PMID 40470773, 2025). "Our study provides critical insights into the role of LINC01094 in the energy metabolism and tumor progression of BC." (PMID 40470773, 2025). "Silencing of LINC01094 in xenograft mouse models notably reduces the proliferation, migration, and metastasis of PC cells, elucidating its role in promoting tumor growth and metastasis." (PMID 39161590, 2024). "LINC01094 dually regulates the expression of PD-L1 and PD-L2 and shapes the immunosuppressive tumor microenvironment via sponging miR-17-5p." (PMID 39525623, 2024). "This variant was associated with the differential expression of LINC01094 in eQTL analysis using normal colon mucosa samples (p = 0.0025) and CCNG2 in tumor tissue samples (p = 0.024)." (PMID 38664626, 2024). "LINC01094 acts as a competitive endogenous RNA in ccRCC and plays a tumor-promoting contribution to the progress of ccRCC through the microRNA 224-5p/chondroitin synthase 1 (CHSY1) regulatory axis." (PMID 36824662, 2023). "Apart from acting as an effective miR-577 sponge, LINC01094 can competitively bind to a variety of microRNAs to promote tumor progression." (PMID 36568382, 2022). "The data showed higher expression of lncRNA DNM3OS, MAGI2-AS3 and LINC01094 in LUSC tumor samples compared with normal tissues." (PMID 36139456, 2022). "Consistently, qRT-PCR assay showed that the expression of LINC01094 in the collected OC samples was markedly higher in comparison with that in adjacent non-tumor tissues." (PMID 33069244, 2020). "Consistent with our findings, it has been reported that LINC01094 plays its pro-tumor role in the development of ccRCC by regulating the miR-224-5p/CHSY1 axis." (PMID 33173535, 2020). "Specifically, LINC01094 functions as a ceRNA to modulate tumor cell growth, invasion, and migration by regulating critical signaling pathways including PI3K/AKT, PTEN/AKT, and Wnt/β-catenin, while also exerting oncogenic effects through transcriptional regulatory networks." (PMID 41623379, 2026). "LINC01094 promotes aerobic glycolysis and tumor progression in BC." (PMID 40470773, 2025). "Next, we established a xenograft tumor model by subcutaneously implanting BC cells transfected with GFP‐expressed lentiviruses LV‐sh LINC01094 or LV‐sh NC into the mammary fat pad of mice to corroborate the role of LINC01094 in regulating BC progression in vivo." (PMID 40470773, 2025). "Correlation analyses further suggested that LINC01094 may be involved in immune- and inflammation-related signaling pathways, as well as tumor progression and metastasis pathways." (PMID 40438104, 2025).
tumor (continued). "Similarly, LINC01094 exhibits significant overexpression in PC tissues based on the GEO database and correlates with unfavorable clinical features, including tumor size, lymphatic metastasis, and TNM classification." (PMID 39161590, 2024). "The measurement on tumor mass and volume showed that overexpression of LINC01094 could promote tumor growth and tumor weight (all p < 0.05)." (PMID 33173535, 2020). "Moreover, functional enrichment of mRNAs significantly correlated with LINC01094 (|R| > 0.3, P< 0.05) indicated that positively correlated genes were enriched in immune- and tumor progression–related pathways, while negatively correlated genes were enriched in metabolic pathways." (PMID 40438104, 2025). "We aimed to investigate the role of LINC01094 in PKM2‐mediated metabolic reprogramming and tumor progression." (PMID 40470773, 2025). "Collectively, a LINC01094/SPI1/CCL7 axis was defined in LUAD, which is potentially linking to macrophage infiltration and tumor development." (PMID 36118415, 2022). "Collectively, this research suggests that LINC01094 binds to SPI1 to promote its nuclear translocation, which further activates CCL7 transcription by binding to its promoter, leading to M2 macrophage accumulation and dissemination of tumor cells." (PMID 36118415, 2022). "Interestingly, we observed that only LINC01094 and MIR3142HG were differentially expressed between tumor tissues and paired adjacent normal tissues." (PMID 35096827, 2021). "In addition, a recent study revealed that LINC01094, a long noncoding RNA that is upregulated in clear cell RCC, works as a sponge of miR-224-5p and exerts tumor-promoting effects in RCC progression." (PMID 33557163, 2021). "In the current study, we indicated that LINC01094 was mainly located in the cytoplasm of ccRCC cells, while we did not detect the localization of the lncRNA in tumor sample, which is also our limitation." (PMID 33173535, 2020). "Taken together, we opine that LINC01094 binds to SPI1 and promotes its nuclear translocation, which therefore binds to CCL7 promoter and activates its transcription, leading to increased chemotaxis and M2 skewing of macrophages in LUAD and aggravated tumor progression." (PMID 36118415, 2022). "We found that the expression of LINC0711, LINC01094 and LINC01614 failed to exhibit an apparent difference between GC samples and non-tumor samples." (PMID 36249015, 2022).